GRPR (gastrin releasing peptide receptor)
Diseases named in the same sentence as GRPR in open-access papers (continued):
Sharing a sentence is not in itself a finding about the gene and the disease.
Alzheimer disease (1 paper, 2007). A progressive, neurodegenerative disease characterized by loss of function and death of nerve cells in several areas of the brain leading to loss of cognitive function such as memory and language. "Abnormalities in the gastrin-releasing peptide receptor (GRPR) pathway inpatients with Alzheimer's disease (AD)." (PMID 29213377, 2007).
amnesia (1 paper, 2007). Pathologic partial or complete loss of the ability to recall past experiences ( AMNESIA, RETROGRADE) or to form new memories ( AMNESIA, ANTEROGRADE). "Moreover, drugsacting at the GRPR have been shown to enhance memory and ameliorate cognitivedysfunction in experimental models of amnesia associated with AD." (PMID 29213377, 2007).
attention deficit-hyperactivity disorder (1 paper, 2017). A disorder characterized by a marked pattern of inattention and/or hyperactivity-impulsivity that is inconsistent with developmental level and clearly interferes with functioning in at least two settings (e.g. at home and at school). "In addition to a gain of the NPY gene in a familial case with EOO and attention deficit hyperactivity disorder, likely pathogenic CNVs included gains of glutamate receptors (GRIK1, GRM7) and the X-linked gastrin-peptide receptor (GRPR), all inherited from obese parents." (PMID 28489853, 2017).
cervicitis (1 paper, 2025). An acute or chronic inflammatory process that affects the cervix. "When analyzing GRPR protein expression in cervical samples, we observed a strong association between its levels and cervical disease severity." (PMID 40242010, 2025). "Conversely, weak GRPR expression occurred in 93.3%, 78.6%, 42.5%, and 28% of cervicitis, CIN3, SCC, and ADC, respectively." (PMID 40242010, 2025). "Importantly, the percentage of samples expressing high GRPR levels increased progressively according to cervical lesion severity." (PMID 40242010, 2025). "Strong GRPR expression increased with cervical lesion severity (p<0.001), with 6.7% of cervicitis, 21.4% of CIN3, 57.5% of SCC, and 72% of ADC samples showing high GRPR levels." (PMID 40242010, 2025).
Crohn disease (1 paper, 2017). A gastrointestinal disorder characterized by chronic inflammation involving all layers of the intestinal wall, noncaseating granulomas affecting the intestinal wall and regional lymph nodes, and transmural fibrosis. "Whether decreased gastrin-releasing peptide receptor expression as seen in patients with Crohn’s disease also affects the extent of the hypergastrinemia seen in dogs with CE has not been determined." (PMID 29115998, 2017).
Ductal Carcinoma (1 paper, 2023). "T47D Breast Epithelial Ductal Carcinoma cells positive for GRPr were used to establish the therapeutic effects in vivo." (PMID 36986728, 2023).
esophageal squamous cell carcinoma (1 paper, 2025). Esophageal squamous cell carcinoma (ESCC) is a type of esophageal carcinoma (EC) that can affect any part of the esophagus, but is usually located in the upper or middle third. "Taken together, these findings support GRPR as a promising diagnostic biomarker for head and neck and esophageal SCC." (PMID 41266536, 2025). "GRPR is overexpressed in head and neck and esophageal squamous cell carcinoma, and higher expression was associated with worse survival, suggesting a promising role of GRPR as a new biomarker for early diagnosis and prognosis." (PMID 41266536, 2025). "Our findings demonstrate the overexpression of GRPR in head and neck and esophageal SCC, with high GRPR levels correlating with worse survival." (PMID 41266536, 2025). "To explore potential site-specific differences in GRPR expression, we also included esophageal squamous cell carcinoma." (PMID 41266536, 2025). "Its performance supports the feasibility of GRPR immunohistochemistry for improving the detection of head and neck and esophageal SCC." (PMID 41266536, 2025). "Consistent with previous findings, our research indicates GRPR overexpression in 72.5% of head and neck and esophageal SCC, with no expression in healthy controls." (PMID 41266536, 2025).
esophageal tumors (1 paper, 2025). "Despite promising results linking GRPR with head and neck and esophageal tumors, few data are available on GRPR immunohistochemistry and its correlation with patient survival." (PMID 41266536, 2025). "We investigated GRPR protein expression by immunohistochemistry in SCC of head and neck and esophageal tumors and evaluated whether GRPR serves as a prognostic biomarker in these tumors." (PMID 41266536, 2025).
Granuloma (1 paper, 2012). A compact, organized collection of mature mononuclear phagocytes, which may be but is not necessarily accompanied by accessory features such as necrosis. "Only two of the 9 GRPR positive granuloma subjects were active smokers." (PMID 22296774, 2012).
intraepithelial neoplasia (1 paper, 2024). A precancerous neoplastic process that affects the squamous, glandular, or transitional cell epithelium without evidence of invasion. "Studies have shown that GRPR expression in atypical glands gradually increases during the progression from normal prostate tissue to high-grade intraepithelial neoplasia (HG-PIN); GRPR expression has also been reported to be inversely correlated with PSMA expression." (PMID 38880858, 2024).
invasive breast carcinoma (1 paper, 2017). A carcinoma that infiltrates the breast parenchyma. "Notably, high GRPR expression levels were documented in >60% of patient biopsy specimens of invasive breast carcinomas by GRPR-autoradiography, whereas all metastases originating from GRPR-positive primaries preserved high GRPR expression status." (PMID 29137110, 2017).
invasive carcinoma (1 paper, 2025). A carcinoma that is not confined to the epithelium, and has spread to the surrounding stroma. "In samples of invasive carcinomas and adenocarcinomas, both nuclear and cytoplasmic GRPR staining was observed." (PMID 40242010, 2025).
kidney damage (1 paper, 2025). "GRPR antagonists can inhibit several pro-inflammatory signaling pathways, prevent the secretion of pro-inflammatory cytokines, and reduce the infiltration of inflammatory cells, thereby mitigating renal inflammation and alleviating kidney damage." (PMID 40509291, 2025). "Our previous research demonstrated that the small-molecule GRPR antagonist PD176252 alleviates CIS-induced nephrotoxicity, whereas RH-1402, a derivative designed based on PD176252, exhibits enhanced renal protective effects by reducing inflammation and mitigating kidney damage." (PMID 40509291, 2025).
lung fibrosis (1 paper, 2021). "GRP was shown to induce the fibrotic response in a murine model of lung fibrosis and in human cell lines, and GRPR antagonism can reverse the effect of GRP on cell proliferation, indicating increased GRPR may be involved in the fibrotic response." (PMID 34912333, 2021).
melanoma (1 paper, 2025). A malignant, usually aggressive tumor composed of atypical, neoplastic melanocytes. "The GRPR antagonist RC-3095 reduced melanoma lung metastases and shows promise in breast, lung, prostate and pancreatic cancers." (PMID 40500450, 2025). "To evaluate GRPR inhibition in vivo, we used luciferase-expressing 1057 ΔEcad female melanoma cells (1057Luc)." (PMID 40500450, 2025). "In a mouse model of melanoma, we discovered an oestrogen-sensitizing pathway connecting E-cadherin, β-catenin, oestrogen receptor-α and GRPR that promotes melanoma aggressiveness in women." (PMID 40500450, 2025). "By contrast, in other carcinomas or melanoma, GRPR is probably activated at metastatic sites by locally produced GRP." (PMID 40500450, 2025). "Ectopic GRPR expression in mouse and human melanoma lines strongly induced (in 1181) or enhanced (in 1014 and 501mel) colony formation." (PMID 40500450, 2025). "GRPR activation reduced apoptosis in unattached mouse and human melanoma cells, indicating resistance to anoikis." (PMID 40500450, 2025). "We used PamGene kinase assays to identify the main pathway activated by GRP/GRPR in melanoma cells." (PMID 40500450, 2025).
metastatic cancer (1 paper, 2024). A carcinoma which has spread from the original site of growth to another anatomic site. "Elucidating the role of GRPR in cancer metastasis is crucial for developing effective therapeutic strategies for patients with metastatic cancer." (PMID 39768218, 2024).
non-small cell lung carcinoma (1 paper, 2011). A group of at least three distinct histological types of lung cancer, including non-small cell squamous cell carcinoma, adenocarcinoma, and large cell carcinoma. "Proof of this concept is provided by a recent pre-clinical study that evaluated the effects of the GRPR antagonist, RC-3940-II, in an orthotopic non-small-cell lung carcinoma model." (PMID 21745389, 2011).
panic disorder (1 paper, 2012). An anxiety disorder characterized by multiple unexpected panic attacks with persistent concern of recurring attacks. "More recently, however, the possibility that GRP and GRPR are candidate genes in panic disorders was not confirmed in an association and linkage analysis." (PMID 23251133, 2012).
prostate (1 paper, 2015). "Although GRPR and its specific peptide have been associated with an oncogenic role in different tissues and models, the present work is the first report ascertaining the malignant impact of this receptor in prostate carcinogenesis." (PMID 26097883, 2015).
psoriasis (1 paper, 2020). An autoimmune condition characterized by red, well-delineated plaques with silvery scales that are usually on the extensor surfaces and scalp. "Collectively, we have demonstrated that itch‐responsive GRPR+ neurons largely contribute to intractable itch in a mouse model of psoriasis." (PMID 32584520, 2020). "The GRP‐GRPR system might be enhanced in the SDH, and itch‐responsive GRPR+ neurons largely contribute to intractable itch in a mouse model of psoriasis." (PMID 32584520, 2020).
schizophrenia (1 paper, 2012). A major psychotic disorder characterized by abnormalities in the perception or expression of reality. "Further studies using samples from patients and animal models are required to examine whether GRPR signaling is involved in schizophrenia." (PMID 23251133, 2012).
squamous cell tumors (1 paper, 2023). "The results show that five of five (100%) primary adenocarcinomas and 10 of 16 (63%) primary squamous cell tumors overexpress GRPR at an IRS score of 6 or higher." (PMID 36761980, 2023).
tongue squamous cell carcinoma (1 paper, 2020). A squamous cell carcinoma that arises from the tongue. "In the present study, we also demonstrated the high expression level of GRPR in primary OSCC tissues by immunofluorescence, and in the human tongue squamous cell carcinoma cell line HSC-3." (PMID 32651409, 2020).
tumor (203 papers, 1999 to 2026). "Emerging radiotracers targeting the GRPR, AR, and amino acid transporters offer a multifaceted diagnostic framework that reflects the tumor heterogeneity and evolutionary dynamics inherent in PCa." (PMID 41226028, 2025). "Both derivatives demonstrated about 82–96% loss of their tumor uptake in blocking studies using unlabeled peptide, proving the GRPR-mediated uptake of radiotracer." (PMID 40430268, 2025). "All variants showed high GRPR-specific tumor uptake, rapid blood clearance, and minimal liver accumulation, which correlated with the hydrophobicity of the X group." (PMID 41251982, 2025). "The findings revealed that among the 1432 tumor cases, the incidence of GRPR overexpression was 75.8%, which was closely linked to a positive ER status." (PMID 38279185, 2024). "Our findings revealed that GRPR levels were significantly elevated in tumor tissues, and higher GRPR expression was associated with worse overall survival outcomes." (PMID 39768218, 2024). "Gastrin-releasing peptide (GRP) and its receptor (GRPR) have been reported to be aberrantly expressed in the colon after malignant transformation and have been associated with delayed tumor recurrence and improved survival." (PMID 35479956, 2022). "The resulting in situ stabilization of circulating BBN-like radioligands maximized their delivery to tumor-associated GRPR sites, thereby improving tumor uptake." (PMID 34830920, 2021). "This upregulation could render hypoxic tumour regions particularly susceptible to GRPR-targeted therapies." (PMID 41226822, 2025). "Thus, the high tumor-to-tissue values clearly demonstrated that 68Ga-labeled novel peptides are promising candidates for further development of diagnostic tracers for GRPR-positive cancers." (PMID 40775579, 2025). "Moreover, a correlation was detected among GRPR expression in BC cells showing ER-positive tumours and indicated the diagnostic and therapeutic potential of GRPR antagonist in BC." (PMID 33925632, 2021). "BBN could bind specifically to GRPR, which is overexpressed in a variety of tumor tissues and is associated with tumor infiltration and growth." (PMID 33532584, 2021). "Finally, the ex vivo binding to various human cancer tissues and the ability to clearly visualize the tumor in a simulated surgical setting underline the potential for future clinical translation of our developed probe for image-guided surgery of GRPR-positive tumors." (PMID 37046825, 2023). "However, the strong physiological action and mitogenicity associated with BN-based GRPR-agonists and the superior tumor uptake seen for somatostatin antagonists led to a paradigm shift towards the use of potent GRPR antagonists in the development of BN analogs during recent years." (PMID 29097932, 2017). "Gastrin-releasing peptide receptor (GRPR) is overexpressed in a range of tumor types, making it an attractive candidate for novel treatment approaches." (PMID 41344852, 2026). "Recently, a new phase I clinical trial has been initiated to explore the safety and anticancer efficacy profiles of [212Pb]Pb‐DOTAM‐GRPR1 in BC patients with tumours expressing GRPR at various levels, as well as other types of cancer (NCT05283330)." (PMID 41555955, 2026). "Targeting and binding to GRPRs present on certain tumor cells; upon binding and internalization, this radioconjugate specifically delivers a cytotoxic dose of beta radiation to GRPR‐expressing cells." (PMID 41510186, 2026). "The radiotracers showed high GRPR-specific tumor uptake and faster blood clearance than DOTA-based analogs." (PMID 41251982, 2025). "A faster clearance from PC-3 tumor xenografts was observed for [177Lu]Lu-TacsBOMB5 compared with other GRPR-targeted ligands." (PMID 40283887, 2025). "[68Ga]Ga-NeoBOMB1 and [177Lu]Lu-NeoBOMB1 showed considerably greater GRPR-specific tumour uptake in PC-3 model mice (30.6 ± 3.9, 28.6 ± 6.0, and more than 35%ID/g, respectively, at 4 h post-injection)." (PMID 39747850, 2025).
tumor (continued). "In this system, DOX was loaded onto GO via π–π interactions and hydrogen bonding, and GRPR antagonist peptide BBN was used for tumor targeting." (PMID 41155020, 2025). "Lastly, the introduction of the Arg residues in the linkers, while resulting in better activity retention in tumours (due to the increase of GRPR-affinity), inadvertently led to increased retention in the kidneys." (PMID 40745236, 2025). "In both models, tumour distribution and uptake were determined using the GRPR-targeted radiotracer [177Lu]Lu-DOTA-SP714." (PMID 40016527, 2025). "With a significantly reduced tumor uptake in the blocked mice, both blocking studies confirmed the specific uptake of [68Ga]Ga-LW02060 and [68Ga]Ga-LW02080 in the GRPR-expressing PC-3 tumor xenografts." (PMID 40006047, 2025). "With regard to specificity and off-target binding, GRPR is also physiologically expressed in several non-tumor tissues, including the pancreas, gastrointestinal tract, and normal breast tissue." (PMID 40647404, 2025). "68Ga-labeled GRPR antagonist SB3 has demonstrated 88% sensitivity in identifying tumor lesions in biopsy-confirmed PCa patients who were therapy-naïve and scheduled for prostatectomy." (PMID 41226028, 2025). "RNA-seq analysis of eight primary tumours per genotype and sex revealed a marked upregulation of gastrin-releasing peptide receptor (Grpr) in ∆Ecad female melanomas compared with all other groups, including ∆Ecad male mice." (PMID 40500450, 2025). "Biodistribution studies at 2 h post-injection in PC-3 xenograft-bearing mice revealed high, GRPR-mediated tumor uptake for all three radioligands." (PMID 40775579, 2025). "Radiolabeled GRPR antagonists are considered safer than agonists and have shown higher tumour uptake and clearance than agonists." (PMID 41049848, 2025). "These three tracers showed high uptake in PC-3 tumor xenografts and minimal pancreas uptake at 1 h post-injection, demonstrating their potential as imaging agents for detecting GRPR-expressing lesions with PET." (PMID 40283887, 2025). "The low activity uptake in tumours was unexpected, especially given the reasonable affinity to GRPR and substantial GRPR-mediated uptake observed in normal pancreatic tissue." (PMID 40138074, 2025). "In PC3-mice, it demonstrated high and specific tumor uptake (45.4 ± 3.9 and 4.9 ± 1.6% I.A./g at 4 and 96 h p.i., respectively), while lower GRPR density in T47D-mice led to reduced uptake (6.1 ± 3.9 and 0.7 ± 0.1% I.A./g at 4 and 72 h p.i.)." (PMID 41217470, 2025). "Persistent high GRPR affinity and specificity were validated using in vivo blocking studies, with a significant reduction in tumor uptake of both 68Ga-labeled monomeric and dimeric TMs when pre-dosed with Ava-BBN2." (PMID 40141329, 2025). "Blocking studies confirmed the GRPR mediated the uptake of both derivatives as tumor uptakes were nearly diminished." (PMID 40430268, 2025). "In a study of 19 tumour samples, GRPR mRNA was present in all specimens, though this appeared to lack prognostic significance." (PMID 40426729, 2025). "When tested in vivo in GRPR expressing PC-3 xenografts, both radioantagonists demonstrated high tumor accumulation (6.3 ± 0.5%IA/g and 5 ± 1%IA/g at 1 h pi, respectively), with good retention over time (4 ± 2%IA/g and 3.1 ± 0.1%IA/g at 4 h pi, respectively)." (PMID 39825204, 2025). "GRPR can be an important indicator of initial molecular changes in PCa development and GRPR scintigraphy can provide a cost-effective option for early tumor detection." (PMID 41226028, 2025). "With the lowest initial uptake in PC-3 tumor xenografts among all evaluated radioligands, the clinically evaluated GRPR agonist [177Lu]Lu-AMBA also had the lowest absorbed dose in PC-3 tumor xenografts (79.1 mGy/MBq)." (PMID 40283887, 2025). "The incorporation of MetTrp8 enhanced the in vivo stability of both peptides, resulting in improved tumor-targeting properties in mice with GRPR-expressing xenografts." (PMID 41231375, 2025).